INS (insulin)
Diseases named in the same sentence as INS in open-access papers (continued):
Sharing a sentence is not in itself a finding about the gene and the disease.
diabetes (continued). "These conditions, mimicking obesity/diabetes-related hyperglycemia and hyperinsulinemia, abrogated insulin-stimulated AKT phosphorylation at Ser473." (PMID 28620170, 2017). "In the case of Diabetes also, our male patient had more severe disease and developed anti-hyperglycaemic treatment failure requiring insulin 5 years after diagnosis, but the female patient still remains well controlled on two anti-hyperglycaemic medications." (PMID 28446151, 2017). "A total of 72 patients who were prescribed insulin for a diabetes diagnosis were included in the National Diabetes Inpatient Audit data collection at the trust, and were therefore eligible for inclusion in the study." (PMID 28852529, 2017). "In this group of patients, insulin threshold of 20 μIU/ml was an adverse outcome predictor at 1 year in type 2 diabetes mellitus with coronary artery disease." (PMID 28529547, 2017). "In an international comparison of physicians practices in managing diabetes, Indian physicians were among the most likely to delay insulin therapy." (PMID 28296920, 2017). "To help address this issue, we assessed insulin availability, prices, affordability and price components in Hubei Province as China has the heaviest burden of diabetes globally." (PMID 28836974, 2017). "Magnesium is a co-factor in several pathways, including glucose transport, insulin sensitivity and insulin secretion, providing a molecular basis for its involvement in the pathogenesis of diabetes mellitus." (PMID 28224192, 2017). "Type 2 diabetes mellitus (T2DM) is characterized by impaired insulin secretion, glucose intolerance, and hyperglycemia." (PMID 28251163, 2017). "The character of diabetes mellitus is hyperglycemia resulting from defects in insulin secretion, insulin action, or both." (PMID 28612706, 2017). "Dietary fatty acids play an important role in cell membranes and insulin sensitivity, interfering with the metabolic control of diabetes." (PMID 29065507, 2017). "Diabetes mellitus (DM) is a heterogeneous group of metabolic disorders that have in common hyperglycemia as a consequence of failure of insulin action." (PMID 28876366, 2017). "In this work, we are interested in the effects that polyphenols have on the secretion and signaling of glucagon-like peptide-1 (GLP1) and insulin, two hormones whose insufficient or inappropriate activity ultimately leads to diabetes." (PMID 28556815, 2017). "Defective hepatic autophagy is observed in obesity and diabetes, whereas autophagy is inhibited by insulin in hepatocytes." (PMID 28740220, 2017). "Concerning the ADDQoL average weighted impact score, we found a significant interaction between DR, the study group (i.e., type of diabetes) and insulin treatment." (PMID 29062603, 2017). "Studies of diabetes patients added that the capacity for insulin secretion and IR are closely affected by TG and FPG levels, which was also confirmed in an intervention study." (PMID 28249577, 2017). "Age, sex, BMI, reconstruction type, diabetes duration, preoperative blood glucose, HbA1c, insulin, C-peptide, HOMA-IR, ghrelin, leptin, GIP, PYY, and GLP-1 were analyzed." (PMID 29216250, 2017). "Significant improvement in diabetes and insulin-related attitudes from the baseline to post-intervention was observed in 4 of the 9 items in the game group, and in 3 of 9 items in the control." (PMID 28279950, 2017). "The terms diabetes, hyperglycemia, insulin, obesity, and others were used as keywords for identification of papers in PubMed." (PMID 28139721, 2017). "Insulin pellets significantly reduced blood glucose levels at 110.65 ± 11 mg/dL and 97.67 ±9.48 mg/dL for 21 and 40 days of diabetes, respectively." (PMID 28273875, 2017). "STZ is a diabetogenic substance used in diabetes research to induce insulin depletion after intraperitoneal injection." (PMID 28422052, 2017).
diabetes (continued). "In diabetes research, MSCs have been involved to generate insulin-producing cells, suppress autoimmunity, and treat the complications of diabetes mellitus such as cardiomyopathy, nephropathy, retinopathy, polyneuropathy, and diabetic wounds." (PMID 28168007, 2017). "Certain probiotic species have improved insulin sensitivity, inflammatory markers and lipid profiles in obese, type 2 diabetes mellitus and dyslipidaemic subjects." (PMID 28069054, 2017). "DIo, a measure of β-cell function adjusted for insulin sensitivity, which is a good predictor of diabetes, differed among 3 groups." (PMID 28878826, 2017). "Diabetes mellitus represents a group of metabolic disorders characterized by increased levels of blood glucose resulting from defects in insulin secretion, insulin action, or both." (PMID 28052112, 2017). "Hepcidin levels were lower in persons with prediabetes compared to control, while persons with diabetes on insulin therapy had higher values than those with prediabetes (p = 0,00001)." (PMID 28841871, 2017). "The fact that diabetes was relatively well controlled with low insulin doses when BMI was in the high range further argues for a causative ABCC8 mutation." (PMID 29112131, 2017). "In contrast, SED-time was positively associated with age, diabetes duration, HbA1c, FPG, insulin, HOMA-IR, BMI, fat mass, waist circumference, triglycerides, systolic BP, hs-CRP, ACR, UKPDS risk scores, and physical fitness measures." (PMID 28291838, 2017). "Ineligible patients were older and more often female than eligible patients, they had a higher HbA1c level, a longer diabetes duration, more microvascular and macrovascular complications, and they used insulin more often." (PMID 28336505, 2017). "Type 2 diabetes mellitus (T2DM) is a metabolic disease characterized by chronic hyperglycemia primarily resulting from defects in insulin secretion, insulin efficacy, or both." (PMID 28207836, 2017). "Once again the mechanisms for the increased in‐stent complications are not known and our data provides supporting evidence for more focused studies in patients with diabetes and macrovascular disease treated with insulin." (PMID 28029209, 2017). "This information is important for women taking insulin and clinicians working with diabetes and breast cancer screening." (PMID 27832382, 2017). "Studies have shown that insulin secretion and islet β-cell function are elevated several years before the onset of diabetes and then decrease until the time of diagnosis." (PMID 28372564, 2017). "Early short-term intensive insulin (STII) therapy can induce drug-free glycemic remission for up to 1 year in half of newly diagnosed type 2 diabetic mellitus (T2DM) patients." (PMID 28539618, 2017). "In diabetes, the levels of free fatty acids are increased and there is a reversed correlation between plasma FFAs and insulin sensitivity in muscles." (PMID 29201096, 2017). "We performed meta-analysis of the pathway expression test for MSigDB gene sets over 13 diabetes studies, five insulin action studies and their combined data sets." (PMID 28117714, 2017). "There is, however, interest amongst people with diabetes and HPs to use diabetes apps, with strong interest in an insulin dose calculator." (PMID 28666975, 2017). "The results obtained in mice with diabetes induced by alloxan suggest that the antidiabetic action of teuhetenone A is similar to insulin, taking into account that with both substances, the glucose level decreases by approximately 35%." (PMID 28397755, 2017). "Our initial experiments confirmed that alloxan successfully induced diabetes in the rabbits after 6 weeks, leading to lower body weight, increased glucose levels and decreased insulin levels compared to control (P < 0.05)." (PMID 28388570, 2017). "Of these tissues, the pancreas plays a central role in the diabetes development, and either destruction of its beta cells or reduction of insulin production will lead to the impaired glucose homeostasis." (PMID 28117714, 2017).
diabetes (continued). "Diabetes is dependent on either the absence or on the malfunction of a single pancreatic hormone, insulin." (PMID 28949988, 2017). "Insulin treatment from the onset of diabetes prevented the decrease in wound healing rate (DM+INS 1.34 ± 0.1 mm2/day)." (PMID 28182694, 2017). "Among individuals with young onset and adult onset diabetes, 40 individuals (1.8% of subjects with early onset diabetes and 0.6% with late onset) were carriers of known pathogenic missense mutations in the GCK, HNF1A, HNF4A, HNF1B, ABCC8, and INS genes." (PMID 29207974, 2017). "In the area of diabetes research, not only insulin but also glucagon is one of the molecules that is difficult to quantify with ELISA3." (PMID 28761041, 2017). "Oxylipins in general, as bioactive signaling lipids, are increasingly being associated with inflammation, vascular permeability, and cardiovascular disease as well as diabetes, obesity-induced hypertriglyceridemia, and insulin signaling." (PMID 28970503, 2017). "It stated that some CDEs have a role in ‘specific aspects of diabetes care, such as insulin initiation and stabilisation’ (, p.11)." (PMID 28702089, 2017). "With respect to baseline glycaemic parameters, patients that progressed to diabetes showed higher values of Hb1Ac, fasting glucose, insulin and HOMA-IR and lower disposition index than subjects who remained as non-diabetic." (PMID 28970513, 2017). "Several studies have shown differentiation of MSCs into insulin-producing cells and their use in ameliorating diabetes in streptozotocin-induced diabetes in rats or mice." (PMID 28701182, 2017). "Hypovitaminosis D is associated with NAFLD, increased insulin resistance, impaired insulin secretion, and is related to type 2 diabetes mellitus (T2DM)." (PMID 29179679, 2017). "Diabetes medication status, biochemical and hormonal data including blood glucose, HbA1c, insulin, C-peptide, HOMA-IR, ghrelin, leptin, GLP-1, PYY, and GIP were evaluated for 12 months after surgery." (PMID 29216250, 2017). "The replacement of IPCs would be the ideal solution for the treatment of diabetes mellitus; however, the generation of insulin-secreting cells from stem cells represents an attractive alternative." (PMID 29290993, 2017). "Type 2 diabetes mellitus (T2DM) accounts for 90–95% of diabetes cases, and is characterized by insufficient pancreatic insulin secretion and insulin resistance." (PMID 29027968, 2017). "Insulin resistance is a condition in which insulin signaling and action are impaired in insulin sensitive tissues and result in hyperglycemia, hyperlipidemia, and type 2 diabetes mellitus." (PMID 29201096, 2017). "Increasing insulin production and reducing insulin resistance are significant for the treatment of diabetes." (PMID 29057036, 2017). "Clinical and preclinical diabetes trials have sought to replace conventional insulin injections with islet implantation." (PMID 30970718, 2017). "Recently, a few researchers have made progress on anti-diabetic therapies using MSNs; however, their approaches are limited to insulin delivery to treat insulin based diabetes by controlled delivery or utilizing MSNs as sensors." (PMID 28498352, 2017). "Some studies have also looked at secondary prevention of diabetes by enforcing self-management of lifestyle behavior, insulin therapy, medications, and physician visits." (PMID 29233806, 2017). "These miRNAs are respectively involved in hepatic insulin sensitivity (miR-181a), expressed in human β-cells (miR-323-3p), identified in PBMCs from people with diabetes (miR-342-3p), and regulated by exercise (miR-151-5p)." (PMID 28846711, 2017). "The combination of GRS, age at diagnosis, clinical phenotype, autoantibody assays, and C-peptide estimates as a proxy for insulin secretion affords a more sophisticated approach with the potential to dissect the heterogeneity of diabetes." (PMID 28438156, 2017).
diabetes (continued). "As a commonly used oral anti-hyperglycaemic agent for type 2 diabetes mellitus (DM), metformin can improve insulin sensitivity by increasing peripheral glucose intake and utilization." (PMID 28103573, 2017). "Kaempferol inhibits NF-κB pathway activation, thus inhibits hepatic inflammation, which is contributing to the improvement of insulin signaling defect in diabetes." (PMID 28729836, 2017). "Eighteen (43%) patients had an error or discrepancy relating to insulin on their discharge summary, 11 (61%) of whom had type 2 diabetes, 6 (33%) had type 1 diabetes and 1 (6%) had cystic fibrosis-related diabetes." (PMID 28852529, 2017). "The results showed that patients with metabolic syndrome, insulin therapy, diabetes and a history of myocardial infarction or percutaneous intervention had higher SFRP4 levels." (PMID 29037197, 2017). "A reduction in GLUT4 protein, the major cardiac glucose transporter, due to reduced transcription in diabetes, and impaired insulin signaling in the diabetic heart result in the observable reduction in glucose uptake." (PMID 28933367, 2017). "The substitution of insulin and enzymes as well as the ability of blood transfusions via blood preserve (1922 Banting and Co. were able to save the first patient with diabetes by substituting insulin) improved the outcome dramatically." (PMID 28819358, 2017). "A multivariate analysis showed that the risk factors associated with CTS were previous wrist fracture, rheumatoid arthritis, osteoarthritis of the wrist, obesity, diabetes, and the use of insulin, sulphonylureas, metformin, and thyroxine." (PMID 28959514, 2017). "The disease burden of diabetes has been steadily rising and improving access to insulin, long considered an "essential medicine" by many countries as well as the World Health Organization (WHO), has taken on increasing importance." (PMID 27446593, 2017). "We conducted a 30-day in-silico study in type 1 diabetes mellitus (T1DM) patients using continuous subcutaneous insulin infusion (CSII) therapy and a variety of BG meters, using the FDA-approved University of Virginia (UVA)/Padova Type 1 Simulator." (PMID 28569076, 2017). "The detection of insulin in diabetes samples has been used in early-diagnosis, monitoring disease progression, prognosis and pathology research." (PMID 28115918, 2017). "For example, the model predicts that “insulin level” is to “Zucker rat” (a spontaneous model of diabetes) what “heart rate” is to “SHR rat” (a model of hypertension)." (PMID 28678787, 2017). "According to results of our study, we conclude that prediabetes is connected with low values of hepcidin when patients are matched for other factors, whereas treatment with insulin corrects hepcidin values in persons with diabetes." (PMID 28841871, 2017). "The clinical onset of type 2 diabetes mellitus (T2DM) is triggered by insufficient insulin secretion from pancreatic β‐cells to compensate for insulin resistance." (PMID 28544529, 2017). "The accelerated transit of nutrients into the small intestine after bariatric surgery has been regarded by some authors as a major cause of diabetes remission, since it stimulates GLP-1 and insulin secretion." (PMID 28185153, 2017). "Aside from poor renal function, other risk factors for hypoglycaemia were seen in these patients such as old age, long duration of diabetes, high glycosylated haemoglobin, and the use of insulin." (PMID 29230420, 2017). "Autoimmune destruction of insulin producing pancreatic β-cells leads to insulin insufficiency and hyperglycemia in type 1 diabetes mellitus." (PMID 28878669, 2017). "An impaired capacity to increase ATP production in beta cells in response to elevated glucose levels is indeed an important defect seen in diabetes, resulting in reduced insulin secretion." (PMID 27796421, 2017).
diabetes (continued). "Despite these limitations, our analyses showed that use of the Accu-Chek Connect system is associated with increased treatment satisfaction, reduced distress, and improved glycemic control among individuals with insulin-treated diabetes." (PMID 29027812, 2017). "Diabetes mellitus is a group of metabolic diseases characterized by chronichyperglycemia resulting from defects in insulin secretion or action." (PMID 29213501, 2017). "The study will include patients who have been diagnosed with one or more of any of the following conditions: heart failure, chronic obstructive pulmonary disease, chronic kidney disease, uncontrolled hypertension, or insulin-requiring diabetes." (PMID 29162557, 2017). "Diabetes mellitus (DM) is a chronic condition that occurs in response to the lack or reduction of insulin production or by the ineffectiveness of the insulin produced, resulting in increased levels of glucose in the blood." (PMID 28193098, 2017). "An increasing number of patients with type 1 diabetes mellitus (T1DM) under insulin injections will switch to CSII treatment during childhood." (PMID 28484424, 2017). "Type 1 diabetes mellitus (T1DM) is an autoimmune condition in which the immune system is activated to destroy the cells in the pancreas which produce insulin." (PMID 29295509, 2017). "Obesity is linked to cardiovascular diseases and increasingly common in type 1 diabetes mellitus (T1DM) since the introduction of intensified insulin therapy." (PMID 28588898, 2017). "The aim for delivering exogenous insulin in patients with diabetes is to imitate as closely as possible the normal physiological insulin secretion as in healthy humans." (PMID 28864917, 2017). "Hypoglycemia remains a common side-effect of the treatment of diabetes with insulin despite the introduction of novel insulins, formulations and methods of delivery, coupled with advances in glycemic monitoring." (PMID 28824815, 2017). "On the other hand, hypertriglyceridemia exacerbates insulin action (insulin resistance), and blood glucose level further exacerbates diabetes." (PMID 29089472, 2017). "We assessed the possible effect of a commercially available bee honey (given orally by gavage at doses of 1 g/kg/day for 4 weeks) on the blood concentrations of glucose, insulin and leptin and body weight of rats with streptozotocin-induced diabetes." (PMID 28127544, 2017). "Twenty-one subjects (7%) were diagnosed either with epilepsy or had a previous history of epilepsy; 7 patients had type 1 diabetes mellitus and were being treated with insulin from early childhood or adolescence." (PMID 28449774, 2017). "Diabetes mellitus is a group of metabolic diseases that are characterized by hyperglycemia and arise from defects in insulin secretion, insulin action, or both." (PMID 28729836, 2017). "Basically, STZ induces diabetes by destroying the insulin secreting pancreatic β-cells, resulting in a decrease in endogenous insulin release." (PMID 29216879, 2017). "Pancreatic beta-cell death adversely contributes to the progression of both type I and II diabetes by undermining beta-cell mass and subsequently diminishing endogenous insulin production." (PMID 28469576, 2017). "Type 2 diabetes mellitus is often treated with insulin-sensitizing drugs called thiazolidinediones (TZD), which improve insulin resistance and glycemic control." (PMID 29056962, 2017). "From a clinical point of view, despite a longer diabetes duration and a higher likelihood to be treated with insulin, women showed a lower prevalence of known diabetes complications than men." (PMID 28222781, 2017). "For example, a patient with Type 1 diabetes mellitus must understand the glucose and insulin physiology, be able to measure blood glucose levels and inject insulin, and feel that careful treatment of his or her condition makes sense." (PMID 28405531, 2017).